CMBL (carboxymethylenebutenolidase homolog)
Description:
Cysteine hydrolase whose endogenous substrates and physiological function are unknown. Catalyzes the hydrolytic activation of several ester-based prodrugs, by cleaving the dioxolone ring to yield their respective active metabolites, diacetyl and CO2. Can thus convert the prodrugs Olmesartan medoxomil and Azilsartan medoxomil into their active metabolites (Olmesartan and Azilsartan), two angiotensin receptor blockers. Is also able to activate beta-lactam antibiotics Faropenem medoxomil and Lenampicillin.
Synonyms: FLJ23617; JS-1
Tractability: PROTAC: ubiquitination databases record sites on it; its protein half-life has been measured.
Target class: Enzyme; Hydrolase
Gene: Protein-coding gene on chromosome 5 (10,275,875 to 10,307,974, reverse strand). Ensembl gene ENSG00000164237.
Subcellular location: Cytoplasm, cytosol
Pathways (Reactome):
Metabolism: Phase I - Functionalization of compounds
Gene Ontology:
Molecular function: hydrolase activity
Biological process: xenobiotic metabolic process
Cellular component: cytosol; extracellular exosome
Genetic constraint (gnomAD): Loss-of-function variants: 10 observed, 21.71 expected, observed/expected ratio (o/e) 0.46, 90% interval 0.28 to 0.78. The upper end of that interval is the gene's LOEUF score, 0.78, which puts it in group 3 of 6, group 1 being the genes least tolerant of losing a copy. Missense variants: 260 observed, 265.28 expected, observed/expected ratio (o/e) 0.98, 90% interval 0.88 to 1.09. Synonymous variants: 90 observed, 93.78 expected, observed/expected ratio (o/e) 0.96, 90% interval 0.81 to 1.14.
Homologues: Orthologues: chimpanzee CMBL (99% identical), macaque CMBL (95% identical), dog CMBL (87% identical), pig CMBL (86% identical), rat Cmbl (84% identical), mouse Cmbl (83% identical), rabbit CMBL (82% identical), guinea pig CMBL (77% identical), tropical clawed frog cmbl (67% identical), zebrafish cmbl (64% identical).
Diseases named in the same sentence as CMBL in open-access papers:
CMBL is named in the same sentence as 8 diseases in open-access papers, as found by Europe PMC text mining. Sharing a sentence is not in itself a finding about the gene and the disease. The quoted sentences say what the papers report.
breast carcinoma (2 papers, 2015 to 2019). "CMBL (carboxymethylenebutenolidase homolog (Pseudomonas)), the most significant down-regulated gene, was found to be highly expressed in liver cytosol, but the association with breast cancer wasn’t reported." (PMID 26103053, 2015). "Therefore, CMBL may also be a potential biomarker for breast cancer subtyping." (PMID 31480430, 2019).
asthma (1 paper, 2024). "Single gene GSEA analysis revealed that HORMAD2, WNT10A, ATP6V1E2, CMBL, ARRDC4, and LPIN2 were primarily involved in Allograft rejection, Arginine biosynthesis, Asthma, and Fatty acid biosynthesis." (PMID 40635857, 2024).
cyst (1 paper, 2015). A sac-like closed membranous structure that may be empty or contain fluid or amorphous material. "Western blot analyses showed expression of expected protein products for CK-19, ANXA3, CMBL and S100A13 in cyst fluids." (PMID 25978681, 2015). "ANXA3 and CMBL were both expressed in the cyst fluids of cPTCs and benign samples without obvious differences between the two groups." (PMID 25978681, 2015).
neuroblastoma (1 paper, 2026). Neuroblastoma (NB) is the most common solid, extracranial childhood tumor. "Six of these genes (CMBL, LY6E, KLRB1, CTSH, CD3D, and PTGDS) were utilized to construct a risk-scoring model that effectively stratified neuroblastoma patients into high- and low-risk groups with significantly distinct clinical outcomes (p < 0.001)." (PMID 41993132, 2026).
cancer (1 paper, 2020). A tumor composed of atypical neoplastic, often pleomorphic cells that invade other tissues. "Third, previous studies of LRRC17, ZHX3, LYPD6B, KIAA2022, and CMBL in cancer still remain paucity despite the importance of them." (PMID 31856408, 2020).
hematological malignancies (1 paper, 2020). "Among the identified seven genes (LRRC17, ZHX3, CD38, AKR1B10, LYPD6B, KIAA2022, and CMBL) in our study, CD38 was well known about its correlation with hematological malignancies." (PMID 31856408, 2020).
CMBL also shares sentences with these, for which no sentence is quoted: lung carcinoma (1 paper); tumours (1).